CD24 (CD24 molecule)
Diseases named in the same sentence as CD24 in open-access papers (continued):
Sharing a sentence is not in itself a finding about the gene and the disease.
hepatocellular carcinoma (continued). "Increased levels of nitric oxide were detected in the cytoplasm of CD24-overexpressing tumor cells, resulting in tumor growth suppression in preclinical hepatic carcinoma xenograft models." (PMID 33260974, 2020). "Now, some studies have demonstrated that CD24 was overexpressed in hepatocellular carcinoma (HCC) tissues and the highly metastatic HCC cell lines." (PMID 33324558, 2020). "CSCs derived from hepatocellular carcinoma have been identified by several potential surface markers, including CD24, CD44, and CD133." (PMID 33351833, 2020). "Targeting CD24 has been shown to induce tumor cell apoptosis and effectively suppress hepatocellular carcinoma in mice bearing HCC xenografts." (PMID 30717444, 2019). "Altogether, we found CD24 is highly expressed in sorafenib-resistant hepatocellular carcinoma tumor cells." (PMID 29844385, 2018). "Here we found that a cell surface molecule, CD24, is overexpressed in tumor tissues and sorafenib-resistant hepatocellular carcinoma cell lines." (PMID 29844385, 2018). "Cluster of differentiation 24 (CD24) is a specific surface marker involved in the tumorigenesis and progression of hepatocellular carcinoma (HCC)." (PMID 28881644, 2017). "And the near-infrared fluorescence imaging revealed that G7mAb aggregate in CD24+ Huh-7 hepatocellular carcinoma xenograft tissue via specific binding to CD24 in vivo." (PMID 28881644, 2017). "For example, high expression of CD24 is correlated with tumor progression and metastasis in hepatocellular carcinoma and bladder cancer, and blocking its activity by ɑ-CD24 antibodies in mouse models reduced tumorigenesis." (PMID 29156825, 2017). "Above, hG7-BM3 specifically bound to membrane CD24 in hepatoma cell lines, and its binding capacity was comparable to that of cG7." (PMID 28881644, 2017). "NDRG2 modulates the adhesion and invasion of hepatocellular carcinoma cells through regulating CD24 expression." (PMID 25889839, 2015). "For example, CD24+ hepatocellular carcinoma cells showed an increased propensity for self-renewal, differentiation and metastasis as well as enriched levels of Sox2 and Oct4 expression." (PMID 26076835, 2015). "As the signal axis of this GDF3-derived CD24-inducing pathway is undetermined, it remains unsettled as to what is the molecular discrepancy between B16 F1/F10 melanoma cells and G-1/G5 hepatoma cells." (PMID 20950440, 2010). "Furthermore, STAT3 promotes the transcription of Nanog in the tumor-initiating cells of CD24-positive hepatocellular carcinoma (HCC)." (PMID 38881902, 2024). "Additionally, CD24-positive cells isolated from hepatocellular carcinoma cell lines exhibited stemness properties, such as self-renewal, chemotherapy resistance, metastasis, and tumorigenicity." (PMID 36900128, 2023). "Furthermore, the study has shown that the interaction of CD24 and Siglec10 can produce immunosuppressive signals, resulting in natural killer cells (NK) dysfunction, allowing hepatocellular carcinoma (HCC) cells to avoid NK cytotoxicity of tumor cells." (PMID 37484024, 2023). "Moreover, high PD-1 expression was correlated with decreased CD24 expression in B cells infiltrating hepatocellular carcinoma tumors, which resulted in decreased cytokine production." (PMID 36013184, 2022). "Hence, we studied the relationship between CD24 and sorafenib resistance in hepatocellular carcinoma." (PMID 29844385, 2018). "To determine whether hG7-BM3 was bound to hepatoma cells through CD24, we used RNA interference to knockdown CD24 in hepatoma cells." (PMID 28881644, 2017). "In hepatocellular carcinoma CD24 level is actually correlated with patients' prognosis." (PMID 20950440, 2010). "miR-2117, functioning as a tumor suppressor, inhibits the self-renewal of CSCs by directly repressing the transcription factor SOX2 in sorted EpCAM+ or CD24+ primary hepatocellular carcinoma (HCC) cells." (PMID 40710326, 2025).
hepatocellular carcinoma (continued). "In addition, CD24 was shown to promote resistance to sorafenib in hepatocellular carcinoma." (PMID 36013184, 2022). "MiR-3064-5p exerted an antiangiogenic role by targeting the FOXA1/CD24/Src pathway in hepatocellular carcinoma (HCC) but oncogenic lncRNA MALAT1 acted as a ceRNA to sponge miR-3064-5p." (PMID 34350110, 2021). "Meanwhile, it has been documented that CD24+ hepatoma cells also express CD133 and CD326, with CD24 expression overlapping with these markers." (PMID 40830621, 2025). "Once internalized by hepatocellular carcinoma (HCC) cells, the nanosphere-AntiCD24 selectively targets HCC cells that overexpress CD24, facilitating the transport of the CD24 protein to the lysosome for degradation." (PMID 39479443, 2024). "Conjugates of anti-CD24 antibody (G7mAb), nitric oxide (NO), or doxorubicin (DOX) inhibit the growth of hepatocellular carcinoma tumors in mice." (PMID 37894750, 2023). "A humanized murine anti-CD24 monoclonal antibody conjugated with monomethyl auristatin E (MMAE), a tubulin inhibitor, exhibited antitumor efficacy in mouse hepatocellular carcinoma models." (PMID 36013184, 2022). "A past study reported the association of SIGLEC10 in impeding NK cell function and poor patient survival in hepatocellular carcinoma (HCC); CD24/SIGLEC10 interaction may thus be involved in regulating NK cell function." (PMID 36371461, 2022). "Recently, a novel scFv able to bind CD24, a target overexpressed by hepatocellular carcinoma (HCC), has been developed, showing a higher accumulation in the hepatocellular carcinoma xenograft mouse model and proving its potential as a therapeutic and diagnostic agent." (PMID 32184825, 2020). "The expression profiles of CD24 in B16 melanoma sublines were parallel to those of GDF3, but hepatoma lines G1 and G5 had impaired the ability to induce GDF3-mediated CD24 expression." (PMID 20950440, 2010). "Huang showed that CD24 mRNA is expressed in 66% of hepatocellular carcinomas (HCC)." (PMID 16539730, 2006). "Subgroup 0 included hepatoma cells specifically expressing GPC3, CD24 and MDK." (PMID 37305578, 2023). "Recent studies on CD24 depletion using siRNA and NDRG2 regulation in hepatocellular carcinoma and shRNA methods in bladder cancer demonstrated the reduction of tumourigenesis and CD24 could be used as a prognostic marker." (PMID 22693526, 2012). "In addition to CD24 blockade, the recombinant human Siglec-10 Fc chimera decreased anti-inflammatory molecules and considerably increased cytotoxic CD8+ cells by blocking Siglec-10 in hepatocellular carcinoma (HCC)-derived single cells." (PMID 37894750, 2023). "Cells that meet the four indexes of CD133+, CD44+, CD24+, and EpCAM+ are defined as human liver cancer stem cells (hLCSCs), and cells that satisfy the four indexes of CD133-, CD44-, CD24-, and EpCAM are defined as non-hepatoma stem cells (non-hLCSCs)." (PMID 31900225, 2020).
prostate carcinoma (51 papers, 2006 to 2026). A carcinoma that arises from epithelial cells of the prostate gland. "We performed CD24 immunohistochemistry in the same core biopsies of prostate cancer with both PTEN loss and retention, which were already analyzed for S473-pAKT." (PMID 39653828, 2025). "Regarding the role of CD24 in human prostate cancer, two previous studies have identified an association between CD24 expression and serum prostatic specific antigen (PSA) relapse." (PMID 33806857, 2021). "Conversely, low CD24 expression is linked to the mesenchymal phenotype of metastatic prostate cancer cells that have characteristics of cancer stem-like cells associated with high Skp2 expression." (PMID 30952903, 2019). "Our results suggest that the high expression of CD24 is linked to the epithelial and less aggressive phenotype of metastatic prostate cancer cells, accompanied by the low expression of Skp2." (PMID 30952903, 2019). "Lastly, we showed an inverse relationship between Skp2 expression and CD44+CD24− cancer stem-like subpopulation, suggesting that Skp2 is a promising marker for prostate cancer susceptibility." (PMID 30952903, 2019). "As Skp2 overexpression has been correlated with poor prognosis in prostate cancer patients, we wanted to reveal whether high CD24 expression would be associated with a better prognosis." (PMID 30952903, 2019). "CD24 is a mucin-like adhesion molecule expressed on the cell surface of multiple different cell types through a glycosylphosphatidylinositol membrane anchor, and high CD24 expression has been associated with more aggressive disease in ovarian, breast, lung and prostate cancer." (PMID 26981578, 2016). "Interestingly, CD24 positivity (membranous or cytoplasmic) of prostate cancer samples was significantly associated to younger patient age and higher pT stages and a higher 3-year prostate-specific antigen (PSA) relapse rate compared with CD24-negative tumours." (PMID 26578846, 2015). "Kaplan-Meier curves and Cox regression analysis of their prostate cancer study showed that CD24 expression was strongly linked to significantly earlier disease progression (relative risk, 3.2), which was especially pronounced in organ-confined or moderately differentiated primary prostate tumors." (PMID 24452533, 2014). "The expression and MFI value (mean fluorescence intensity) of CD24 were significantly higher in prostate cancer tissues than in prostate paracancerous and benign prostate hyperplasia tissues." (PMID 39687458, 2024). "The cell surface molecule CD24 promotes prostate cancer progression by destabilizing ARF protein by inhibiting NPM–ARF interactions." (PMID 38870055, 2024). "This evidence suggests that CD24 as an oncogene can be an important determinant of prostate cancer aggressiveness." (PMID 39687458, 2024). "In the specific context of prostate cancer, limited studies have delved into the relationship between CD24 expression levels and prognosis." (PMID 39687458, 2024). "Specifically concerning prostate cancer, the expression of CD24 in the cytoplasmic/membrane has been proposed as a means to differentiate between patients with a low or high risk of recurrence." (PMID 39687458, 2024). "The findings were in accordance with the present results, which showed a higher expression of CD24 in prostate cancer patients than in those with BPH." (PMID 39687458, 2024). "Intracellular CD24 in prostate cancer cells is found to encourage cell proliferation but inhibit apoptosis, resulting in tumor progression and metastasis, according to a functional analysis." (PMID 39687458, 2024).
prostate carcinoma (continued). "Due the possibility of using dogs as druggable models for prostate cancer, we performed a homology analysis of human and canine CD24 gene and protein." (PMID 33806857, 2021). "Different therapies targeting CD24 have been proposed recently and the overexpression of CD24 in prostate cancer, as demonstrated in our study, further supports their applicability." (PMID 33806857, 2021). "Since dogs present CD24-positive tumors and CD24 protein have a high protein homology between species, CD24-positive canine prostate cancer can be a valuable model to evaluate the clinical efficiency of this new therapy." (PMID 33806857, 2021). "In this study, we investigated the potential prognostic value of CD24 in prostate cancer through a systematic review of the previous literature on the expression of CD24 in human PC." (PMID 33806857, 2021). "Seventy-eight manuscripts on CD24 expression in human prostate cancer were identified in the original search." (PMID 33806857, 2021). "In the evaluation of CD24 immunoexpression of canine prostate samples, a tendency for a higher survival time was observed in patients with CD24-negative prostate cancer (hazard ratio: 2.235)." (PMID 33806857, 2021). "CD24 induces metastasis to bone and cancer stemness by activating Wnt/β-catenin signaling in prostate cancer in vivo." (PMID 34685470, 2021). "CD24 is a cell surface molecule anchored by glycosyl-phosphatidyl-inositol and expressed by different human cancers, including prostate cancer (PC)." (PMID 33806857, 2021). "FH535, a Wnt signaling inhibitor, reduces prostate cancer cell migration in vitro which corroborates the notion that CD24-mediated Wnt/β-catenin signaling controls cell migration and stemness." (PMID 34685470, 2021). "There is a positive correlation between the CD24 expression of Wnt-mediated bone metastasis of prostate cancer cells in vitro and in vivo." (PMID 34685470, 2021). "In prostate cancer, CD24 colocalizes and copurifies with NPM, a nucleolar phosphoprotein that shuttles between the cytoplasm and the nucleus during the cell cycle." (PMID 34360932, 2021). "Compared to normal tissue, prostate cancer samples had also reduced numbers of CD24- and CD38-positive cells." (PMID 34019593, 2021). "In bladder cancer, prostate cancer, and gastric cancer, hypoxia significantly up-regulated the expression of CD24 mRNA and protein in cancer cells." (PMID 32765491, 2020). "Microarray analyses of prostate cancer cells suggested that CD24 had a role as a growth-promoting factor, which was downregulated when the enzyme adenosine monophosphate kinase (AMPK) was inactivated." (PMID 30405620, 2018). "It was reported that the CD133+ cancer-initiating population and CD44+CD24- putative PCSCs in prostate cancer cell lines are AR+." (PMID 28400729, 2017). "CD24 staining was homogenous and strong in small prostate carcinomas, although differences in intensity and distribution were apparent." (PMID 26978528, 2016). "ALDH alone was also used as an expression marker in both breast and prostate cancer to identify a distinct population of stem-like cells in addition to the CD44+/CD24- fraction." (PMID 27457474, 2016). "Similar to our findings, pronounced intratumoral heterogeneity of CD24 expression has also been described for human prostate carcinoma, and only a proportion of human invasive prostate carcinomas were found to be positive for CD24." (PMID 26978528, 2016).
prostate carcinoma (continued). "The assessment of CD24 as a potential prostate cancer biomarker through RNA expression profiling and IHC analysis in previous studies further illustrates the difficulties in directly comparing gene and protein expression levels." (PMID 18501003, 2008). "We identified a CD44+CD24− subpopulation with varying abundance in different prostate cancer cell lines." (PMID 18268494, 2008). "Normalized CD24 transcript levels showed an average 2.69-fold increase in prostate cancer as determined by qPCR and an increase in staining intensity as determined by IHC." (PMID 18501003, 2008). "The high heterogeneity of CD24 expression even within a tumor of the same individual is apparently a problem not only for the CD24 immunohistochemistry of the prostate carcinoma but also for other tumor entities." (PMID 16539730, 2006). "Gene expression profiling has recently shown that the mRNA for CD24 is overexpressed in prostate carcinomas (Pca) compared to benign or normal prostate epithelial tissues." (PMID 16539730, 2006). "CD24 is also broadly documented as a driver of tumor proliferation and a predictor of poor prognosis in a variety of cancers, including gastric, colorectal, cervical, breast, and prostate cancers." (PMID 38214542, 2024). "Canine prostate cancer expressing CD24 may represent a potential comparative perspective to study the role of CD24 as prognostic and predictive factor in both species." (PMID 33806857, 2021). "Overall, our results demonstrated a significant CD24 overexpression in human and canine prostate cancer, although its prognostic value may be questionable." (PMID 33806857, 2021). "Therefore, future studies investigating the role of CD24 expression on prostate cancer can use these cellular systems to understand the role of this molecule in different cellular processes." (PMID 33806857, 2021). "Only 2/496 prostate cancer patients show CD24 amplification." (PMID 31244889, 2019). "Interestingly, the fraction of the CSC-like CD44+/CD24-subpopulation differs among various prostate cancer cell lines and comprises only 0.04% of LNCaP cells compared to ∼11% of PC-3 cells." (PMID 30542512, 2018). "Activation of TGF-β signal expanded the CD44+CD24- population in prostate cancer cells through downregulating poly r(C) binding protein (PCBP)-1, which suggested that TGF-β might regulate PCSC maintenance." (PMID 28400729, 2017). "Indeed, we found that the clones that highly expressed E-cadherin (Du145-EL and PC3/M-EL) contained many more CD44+/CD24- prostate cancer TICs than the E-cadherin-low clones (Du145-ML and PC3/M-ML)." (PMID 29137367, 2017). "In prostate tumors developing in TRAMP mice, CD24 expression was strong within hyperplastic lesions in comparison with non-hyperplastic regions, and heterogeneous CD24 expression was maintained in advanced prostate carcinomas." (PMID 26978528, 2016). "Some studies have shown that CD24 is highly expressed in high-grade prostate cancers." (PMID 25864518, 2015). "Taken together, this evidence supports the hypothesis that CD44+CD24− cells are the tumour-initiating cells in the prostate cancer cell lines." (PMID 18268494, 2008). "Although, based on these studies, CD24 could potentially be an important prognostic prostate cancer tissue marker, the relationship between mRNA levels and resulting protein expression remains unclear." (PMID 18501003, 2008).